TNF (tumor necrosis factor)
Diseases named in the same sentence as TNF in open-access papers (continued):
Sharing a sentence is not in itself a finding about the gene and the disease.
colitis (continued). "Moreover, the combinatorial treatment with ICIs and immunosuppressive therapy such as TNF-α blockade-vedolizumab may suppress ICI-induced colitis in patients with UC-related dysplasia/colitic cancer and exert antitumour effects." (PMID 34158547, 2021). "Trinitrobenzene sulfonic acid (TNBS) treatment, which is used in animals to induce colitis-like gut inflammation, leads to increased brain TNF-α and reduced memory performance in mice, supporting an association of gut–brain interaction, elevated brain TNF-α, and decreased memory." (PMID 34572019, 2021). "Moreover, chemical-induced colitis in the VDR knockout mice was accompanied by high colonic expression of inflammation, including TNF-α, IL-1α, IL-1β and IL-8, leading to weight loss, ulceration and perforation of the bowel, endotoxemia and increased mortality." (PMID 34576700, 2021). "The association between TNFα and the intestinal microbiota could also explain our previous observation of differences in colitis severity across three independent experiments in non-colonized rats despite consistent experimental conditions." (PMID 33499240, 2021). "A similar trend was observed in our previous studies, which revealed that mice with colitis subjected to voluntary moderate training or forced moderate training had significantly elevated adiponectin plasma levels, while plasma concentrations of leptin, TNF-α, IL-6 and IL-13 were markedly reduced." (PMID 33557311, 2021). "For example, knockout of CerK aggravates the pathology in mice with experimental colitis, C1P exerts protective effects by determining the up-regulation of prostanoids, and down-regulates, in different cell systems, the secretion of pro-inflammatory cytokine TNF-α." (PMID 34209043, 2021). "S. japonicum infection also showed potential for attenuating DSS-induced colitis in Kunming mice, a feature which has been linked to decreased Th1, Th2 and Th17 responses, characterized by a significant decrease in the serum levels of IL-6, IL-2, IL-10, IL-17, IFN-γ and TNF-α." (PMID 33692793, 2021). "Interestingly, HIF-2α deletion in a mouse model of moderate DSS-induced colitis was shown to be protective, whereas genetic HIF-2α overexpression in intestinal epithelial cells resulted in spontaneous DSS colitis via increased expression of TNF-α, IL-1β, and IL-6." (PMID 34571989, 2021). "In berberine‐administrated mice with colitis, levels of such pro‐inflammatory cytokines in the colon and sera were significantly decreased, which was accompanied by a reduction in colonic macrophages and percentages of IL‐6+, IL‐1β+ and TNF‐α+ secreting macrophages among splenocytes." (PMID 33135395, 2020). "DSS-induced colitis induces the massive infiltration of T and B lymphocytes, neutrophils, granulocytes, and macrophages, and they express various pro-inflammatory cytokines, including tumor necrosis factor (TNF)-α; interleukin (IL)-6, IL-8, IL-12, and IL-17; and IFN-γ." (PMID 32485960, 2020). "Additionally, TNF-α gene expression was significantly reduced in the colitis + TOE group." (PMID 33092149, 2020). "Specifically, in a mouse model of acute colitis, administration of oleuropein-loaded lipid nanocarriers significantly reduced TNF-α release and intracellular ROS strongly suggesting that phenols in the extracts may be considered valuable compounds for pharmaceutical applications." (PMID 33374501, 2020). "SCFAs treatment may also constitute substrates for gut mucosa and ameliorate intestinal damage, by restoration of glutathione levels and reduction in proinflammatory mediators, including nitric oxide (NO) and tumor necrosis factor-α (TNF-α) in rat models of colitis." (PMID 33363537, 2020). "Moreover, in mice with colitis, metyrapone inhibited TNF-α-induced glucocorticoid synthesis." (PMID 33255713, 2020).
colitis (continued). "Another study performed in mice model of experimental colitis has shown that treatment of colitic mice with EcN_OMVs could reduce intestinal inflammation by inhibiting the expression of IL-1β, TNF-α and IL-17 and enhancing the expression of IL-10 in colonic tissues." (PMID 32854612, 2020). "Similarly, DMF diminished the expression of NF-κB p65, IL-1β, and TNF-α in experimental colitis." (PMID 32344663, 2020). "In a colitis mouse model, SAA1/SAA2 double knockout mice displayed increased weight loss, histological disease scores and TNF-α expression, suggesting that SAA1/SAA2 may provide protection at the intestinal epithelial barrier through its direct antibacterial properties." (PMID 32477346, 2020). "In addition to mTOR, the phosphatidylinositol 3-kinase-γ (PI3K-γ, upstream of mTOR) have been shown to modulate C. jejuni-induced colitis independently of T cell activation by recruitment of neutrophilic granulocytes to the infected intestines and subsequent massive TNF secretion." (PMID 32231139, 2020). "Likewise, TRYP was found to be effective in protecting mice against experimentally-induced colitis via regulation of the tumor necrosis factor (TNF)/nuclear factor (NF)-κB and interleukin (IL)-6/signal transducer and activator of transcription 3 (STAT3) signaling pathways." (PMID 32792961, 2020). "Thus, preventing MLCK1 recruitment to the perijunctional actomyosin ring may be a non-toxic approach to limiting or preventing immune-mediated colitis either alone or in combination with immunomodulatory agents, e.g., anti-TNF." (PMID 32028590, 2020). "However, rosiglitazone may function through a PPARγ-independent pathway to suppress IL-6, TNF-α, and IL-1β production, as rosiglitazone administration attenuates colitis in IEC-specific PPARγ KO mice." (PMID 30804707, 2019). "Treatment with UroA/UAS03 significantly protected from DSS-induced colitis as evident from decreased gut permeability, reduced shortening of colons, increased colon weight/length ratio, reduced inflammation (serum IL-6, IL-1β, TNF-α as well as colonic tissue MPO levels)." (PMID 30626868, 2019). "Interestingly, epithelial-specific human VDR transgenic mice are protected from developing colitis due to the preservation of the mucosal barrier and protection of IECs from apoptosis through blocking TNF-α-induced p65 binding to the κB site of the PUMA gene promoter." (PMID 30804707, 2019). "As is known to all, IL-1β and TNF-α are representative cytokines that aggravates colitis, the down-regulation of these cytokines caused by Sal treatment in DSS-induced colitis mice might help ease disease." (PMID 31849652, 2019). "In addition, TNF-α-induced claudin-1 upregulation leads to ERK and SRC signaling activation, thus contributing to EMT and increased tumor invasion, suggesting the underlying role of claudin-1 in triggering colitis and CAC." (PMID 31316506, 2019). "Another is to collaborate with cytokines, particularly, TNF‐α, to enhance NF‐κB activation and the induction of COX‐2 to self‐amplify this signalling, which is seen in inflammation driven by macrophages such as in IA and neutrophil‐driven inflammation in colitis‐associated cancer." (PMID 30381825, 2019). "A characteristic of DSS-induced colitis is the momentous infiltrates in the inflammatory lesions, composing mainly of T and B lymphocytes, macrophages, and neutrophils that produce a variety of proinflammatory cytokines such as TNF-α, IL-6, IL-8, IL-12, IL-17, and IFN-γ." (PMID 31780866, 2019). "However, therapeutic administration of TNFα reduced colitis and histopathology." (PMID 30995806, 2019). "It is possible that other mechanism, such as an apoptosis based one may underlie colitis mouse models response to anti-TNFα therapy, not TNFα neutralization." (PMID 31238939, 2019).
colitis (continued). "Acute and chronic DSS-induced colitis leads to higher disease activity and colonic inflammation in Gpr43 KO mice compared to WT littermates, as characterized by increased histological score, neutrophil infiltration together with TNF-α and IL-17 protein levels in the colonic mucosa." (PMID 30915065, 2019). "DSS-induced colitis disrupts the epithelial barriers, allowing intestinal bacteria to invade the damaged mucosa and inducing excessive production of pro-inflammatory cytokines that could be reduced with anti-TNF therapy." (PMID 31238939, 2019). "Therefore, the antiacute colitis activity of JGT may be regulated by its inhibition effect on TNF-α expression." (PMID 30800169, 2019). "In contrast, during the acute phase of DSS-induced colitis model the innate immune cells, especially neutrophils and macrophages, massively infiltrate the LP, and elevated levels of the pro-inflammatory cytokines they secrete, such as TNFα, IL-1β, and IL-17 are observed." (PMID 30619283, 2018). "Thus, we examined the expression of memory markers (CD44 and Eomes), NK cell receptors (NKG2D and Ly49a), cytolytic molecules (FasL and Perforin), and pro-inflammatory cytokines (IFNγ and TNFα) in MLN-derived NK1.1+CD8+ T cells from Yeti/CD1d KO mice during DSS-induced colitis." (PMID 30333822, 2018). "In addition, the administration of apelin to Il10−/− mice with established colitis resulted not only in an amelioration of disease by lowering the production of pro-inflammatory cytokines such as TNFα, IL-6, and IL-1β but furthermore enhanced intestinal lymphatic function." (PMID 30369924, 2018). "Notably, HIF-1α and HIF-2α can oppose each other during intestinal inflammation: for example, epithelial cell HIF-1α helps maintain intestinal barrier functions during colitis, whereas HIF-2α worsens colitis by promoting tumor necrosis factor alpha (TNFα) production in epithelial cells." (PMID 30455703, 2018). "In an experimental model of DSS- or pathogenic bacteria-induced colitis, RA was shown to attenuate inflammation by increasing IL-22 production by ILC3 and Tγδ cells and, consequently, increasing the synthesis of antimicrobial peptides or by decreasing TNF levels and NFκB activation." (PMID 30158832, 2018). "Importantly, cytokines including IL-6 and TNF-α are also increased in TNBS colitis, are known to alter colonic nerve function and may also contribute toward altered CMMC." (PMID 29933379, 2018). "Colon tissue from vehicle-treated mice had higher levels of TNF-α, IL-6, and IL-1β than did colon tissue from mice treated with the probiotic complex or the combination drug; the latter exerted the greatest effect on colitis (p < 0.001, p < 0.001, and p < 0.01, respectively)." (PMID 29466999, 2018). "Moreover, miR-16 has lately been shown to reduce TNF-α and IL-12p40 levels, putatively suppressing mucosal inflammation and thereby resulting in the relief of symptoms in a colitis mouse model suggesting miR-16 as a potential therapeutic target for the treatment of Crohn’s disease." (PMID 29089619, 2017). "However a role of TNF-α in the regulation of NHE-2 is discounted in the present model of colitis." (PMID 28493993, 2017). "Moreover, in these models rolipram suppressed the release of colonic TNF-α, improved the histological score, and reduced collagen production, being effective in both the prevention of intestinal fibrosis and the treatment of established colitis." (PMID 28617319, 2017). "Thus, the anti-TNFα antibody efficiently diminished colitis in the IL10−/− mouse model." (PMID 28566745, 2017). "The data show that oral administration of MORE and MOHRE can significantly decrease the serum levels of TNF-α, IL-6, and IL-17 in colitis mice, suggesting that MORE and MOHRE could suppress the production of proinflammatory cytokines and then relieve the inflammatory response." (PMID 28824631, 2017).
colitis (continued). "In support of this data, rats supplemented with iron and exposed to DSS-induced colitis revealed an increased neutrophil infiltration, TNFα and IL-1 expression and NF-κB activation – all of which could be prevented by supplementing the diet with VitE (dl-alpha-tocopherol acetate)." (PMID 28804483, 2017). "Intestinal damage secondary to murine DSS-induced colitis, ischemia/reperfusion injury total body irradiation and infectious colitis are all associated with a robust inflammatory response, and specifically, with robust expression of the inflammatory cytokines, IL1β, IL10, and TNFα." (PMID 28257503, 2017). "In addition, TNF-α transcriptionally regulates iNOS and COX2; swimming-mediated inhibition of TNF-α gene expression may also be a mechanistic link between such molecules and the suppression of colitis." (PMID 28030847, 2017). "Moreover, G-MDSC exo reduced the serum levels of IFN-γ and TNF-α in DSS-induced colitis mice." (PMID 26885611, 2016). "Administration of P on TNBS colitis after high I. supplementation resulted in a significant improvement of the overall histological score and three individual histological parameters and significantly reduced the levels of t-TNF-α (16.6 ± 5.6 versus 11.85 ± 1.3, P = 0.001)." (PMID 24895596, 2014). "However, during colitis many proapoptotic cytokines like TNF-α are likely to be present, which might interfere with OSM-mediated effects on apoptosis in vivo." (PMID 24710357, 2014). "Enhanced EGFR expression induced by TNF-α promotes GPCR-mediated EGFR transactivation in colonic myofibroblasts, providing an important mechanism for stromal COX-2 over-expression that may predispose to the development of colitis-associated cancer." (PMID 23688423, 2013). "However, DSS- and TNBS- induced colitis have been found to be increased in colonic TNF-α levels." (PMID 24349609, 2013). "By contrast, we found elevated serum levels of TNFα in Mttp-IKO mice, both at baseline and following DSS treatment, suggesting that blocking chylomicron formation was associated with increased production or altered turnover of this proinflammatory cytokine in the setting of acute chemical colitis." (PMID 23805328, 2013). "Rivastigmine 1 and 2 mg given rectally to rats with colitis induced by rectal administration of 30 mg dintrobezene sulfonic acid (DNBS) also caused a dose related reduction in ChE activity in blood and colon, the number of ulcers and area of ulceration, levels of TNF-α and in MPO activity." (PMID 23469045, 2013). "The colitis symptoms share several features with both CD and UC (e.g., chronic, progressive disease with diarrhoea and weight loss, heavily inflamed colon—occasionally transmural damage, loss of mucus from goblet cells, Th1/Th17 dominated cytokine profile as found in CD (IFN-γ, TNF-α, and IL-23)." (PMID 22536543, 2012). "Thus, it is very necessary to dissect the role of TNF signaling via TNF-R1 or 2 in experimental colitis, given that the beneficial outcome of complete blocking TNF may be achieved from blocking the signaling from only one of the two receptors." (PMID 23285227, 2012). "To investigate the mechanism of DSS colitis-induced down-regulation of hepcidin, we considered the possibility that TNFα might be involved, since expression of this cytokine is elevated in the colon and liver (data not shown) as part of the inflammatory process." (PMID 22675442, 2012). "Therefore, it is likely that the immunomodulatory actions of MSCs, including TNF-α suppression could actually play an effective role in preserving the extra cellular matrix of the TNBS-colitis model." (PMID 22432015, 2012). "Although TNF production has been widely considered to be be pathogenic in IBD, these data indicate that the ability to produce normal levels of TNF actually protects against the spontaneous development of colitis in response to intestinal colonization by bacteria." (PMID 22848611, 2012).
colitis (continued). "This is consistent with our previous experiments, and suggests that, despite being crucial pro-inflammatory cytokine produced by macrophages, TNF-α could be either exhausted or downregulated by IL-10, cytokine inhibiting TNF-α production, at this stage of colitis." (PMID 22132181, 2011). "Validation in a Dextran sulfate sodium (DSS)-induced murine colitis model confirmed that oral BBR/CUR@MC acts through dual mechanisms: first, by targeting the TNF signaling pathway to suppress inflammatory cascades." (PMID 41585440, 2026). "In our study, SC significantly reduced TNF-α, IL-1β, IL-8, and IL-18 levels in UC mice, reinforcing its anti-inflammatory potential against DSS-induced colitis." (PMID 39936162, 2025). "By stopping the production of TNF-α, IL-6, and IL-1β in animals with DSS-induced colitis, AVE was shown to have anti-inflammatory effects in this study." (PMID 40699788, 2025). "Strong TNF-α immunoreactivity was observed in rats with TNBS-induced colitis, while it was moderated in 10 mg/kg dose of RES pre-treated group relative to very low TNF-α intensity in control samples." (PMID 40565241, 2025). "In contrast, the insufficient barrier function of IECs and microbial invasion increase the production of pro-inflammatory cytokines, including TNF-α, IFN-γ, and IL6, during intestinal inflammation in murine DSS-induced colitis and human UC and CAC." (PMID 39631567, 2025). "The study in this work demonstrated that supplementation with CW prevents the excessive formation of TNF‐α, IL‐1β, and IL‐6 in the serum of mice with DSS‐induced colitis." (PMID 39830908, 2025). "In the current study, AVCP administration significantly reduced the elevated serum levels of IL-1β, IL-6, TNF-α, and IL-17A induced by DSS in mice, which suggests that AVCP can reduce inflammation in colitis mice." (PMID 40507195, 2025). "The expression of colitis‐related genes, including COX‐2, TNF‐α, IL‐6, and IL‐10, was detected in the colon using RT‐qPCR." (PMID 39803293, 2025). "When the immune system detects these pathogens, it triggers inflammatory cytokines such as tumor necrosis factor-α (TNF-α), interleukin-6 (IL-6), and nitric oxide, which induce colitis." (PMID 39949663, 2025). "Under the anti-inflammatory properties, in the TNBS-induced colitis model, placenta tissue-derived MSC-EVs significantly reduced levels of IL-6 and TNF-α, contributing to the amelioration of disease severity and improved histological architecture." (PMID 41551594, 2025). "In the CSA cohort, vehicle-treated colitis mice exhibited marked elevations in IL-6 (p < 0.001), IL-1β (p < 0.0001), MCP-1 (p < 0.0001), and TNF-α (p < 0.0001) compared to healthy controls." (PMID 40869234, 2025). "In dextran sodium sulfate (DSS)-induced colitis in C57BL/6 mice, verbascoside alleviated disease symptoms, modulated cytokine expression (upregulated IL-10, downregulated IL-1β and TNF-α), and inhibited JAK2/STAT3 and NF-κB pathways." (PMID 40724000, 2025). "Berberine reduces HIF-1α levels by 40% in colonic tissue of DSS-induced colitis mice by downregulating the TLR4/NF-κB/HIF-1α axis, concurrently decreasing TNF-α and IL-6 secretion and alleviating inflammatory infiltration." (PMID 41480384, 2025). "Our findings demonstrate that Indoximod significantly reduced colonic TLR4 expression and plasma levels of TNF-α and PTX3 while also improving histopathological damage in rats with acetic acid-induced colitis." (PMID 40572721, 2025). "The anti-inflammatory effect of probiotics has been confirmed TNF-a, IFN-γ, IL-10, and IL-1β in the DSS-induced colitis mouse model." (PMID 40219015, 2025). "Specifically, the abundance of Bacteroides and Escherichia-Shigella as opportunistic pathogens was significantly positively correlated with key pathological markers of colitis such as MPO, MDA, TNF-α, IL-6, and IL-1β." (PMID 41010513, 2025).